MMP2 (matrix metallopeptidase 2)
Diseases named in the same sentence as MMP2 in open-access papers (continued):
Sharing a sentence is not in itself a finding about the gene and the disease.
breast cancer (continued). "Tomatine, which is a secondary metabolite from tomato, suppresses MMP-2 and MMP-9 activities and cell proliferation in breast cancer MCF-7 cell line and structure-activity relationships of α-, β1-, γ-, and δ-tomatine and tomatidine against various cancer cells have been studied." (PMID 31941156, 2020). "Moreover, astrocyte-derived MMP-2 and MMP-9 have also been shown to promote tumor cell invasion in breast cancer brain metastasis." (PMID 32481745, 2020). "It remained unclear though, whether extracellular MMP2, CTGF and FN1 facilitate invasion in breast cancer interdependently." (PMID 33087801, 2020). "TGF-β/Smad signaling can upregulate MMP2 and MMP9 to induce breast cancer cell invasion." (PMID 32226772, 2020). "However, expression of the matrix metalloproteinase 2 (MMP2), a regulator of breast cancer cell invasion and metastasis generally enriched at the invadopodia, is decreased in PyMT;Pipp−/− tumours." (PMID 33276499, 2020). "Daucosterol linoleate suppresses VEGF, MMP2, and MMP9 expression in breast cancer." (PMID 33426081, 2020). "Indeed, we also found that the levels of MMP-2 and MMP-9 in oral cancer cells or breast cancer cells are higher than in human gingival fibroblasts under the stimulation of PM." (PMID 32922544, 2020). "Although CXCL12, CCL2, VEGF, MMP2, LOX, and CXCR4 were highly associated with HIF-1α expression, their prognostic significance in breast cancer is less so they were not chosen for further immunohistochemistry analyses." (PMID 33003428, 2020). "Similarly, PERK also contributes to ECM reorganization in breast cancer and overexpression of ATF4, which is a component of PERK pathway, induces cell invasion and metastasis, stimulating MMP2 and MMP7 expression in ESCC." (PMID 33014334, 2020). "Moreover, surfactin can inhibit PM-induced cell migration and invasion via inhibition of MMP-2 and MMP-9 expression in various cancer cells including oral cancer cells and breast cancer cells." (PMID 32922544, 2020). "Moreover, TNFα activates the MAPK/ERK signaling pathway and subsequently promotes the migration of breast cancer cells through the upregulation of MMP9, MMP14, and MMP2 in the lipid rafts." (PMID 32986377, 2020). "Mechanistically, we showed that both knockdown of PTTG1 expression and simvastatin treatment potently attenuated breast cancer cell invasion, presumably through inhibition of the expression of PTTG1 downstream target genes, such as MMP-2, MMP9, c-myc, FGF-2, and cyclin D3." (PMID 33250768, 2020). "Matrix metalloproteinase-2 (MMP-2) and MMP-9 have been suggested to promote the invasion of breast cancer cells and we thus reasoned that these factors could be mediators of the invasive potential of breast cancer cells through IL-22." (PMID 31935914, 2020). "In addition to an upregulation of transcription factors, we found an increased expression of IL1RN and the matrix metalloproteinases MMP2 and MMP3 in PRAME overexpressing breast cancer cells." (PMID 30602372, 2019). "Moreover, the mediated epigenetic induction of TIMP-3 levels has played a key role suppressing the invasiveness and gelatinolytic activity of matrix metalloproteinases-2 and 9 (MMP2 and MMP9) in breast cancer cells." (PMID 31505792, 2019). "In addition, SDF-1α binds to CXCR7, another chemokine receptor that is highly expressed on breast cancer cells, and enhances CXCR7-mediated tumor migration and metastasis by activating STAT3, MMP9, MMP2 and VCAM-1." (PMID 31219799, 2019). "Matrix metalloproteinase (MMP) family such as MMP2 and MMP9, the vital epithelial-mesenchymal transition (EMT)-related factor vimentin, and the actin-bundling protein fascin play essential roles in breast cancer metastasis." (PMID 31186039, 2019). "In mice containing cells transfected with MMP, the metastatic ability of cancer cells was significantly enhanced, indicating that MMP-2 and MMP-9 may promote invasion and metastasis of breast cancer." (PMID 31514467, 2019).
breast cancer (continued). "The pronounced secretion of TGFβ1 by CAFs in breast cancer promotes an aggressive phenotype in tumor cells also through direct activation of EMT, with decreased expression of E-CADHERIN and over-expression of VIMENTIN, Fibronectin1 (FN1), MMP2 and MMP9." (PMID 30927908, 2019). "Furthermore, western blotting analysis showed that knockdown of RAI14 inhibits the expression of MMP2 and MMP9 in breast cancer cells." (PMID 31772666, 2019). "We also found that GTN attenuated MMP-2 secretion in both adherent and suspension (spheroid) MDA-MB-231 cell culture, which could reduce the potential of breast cancer cell migration and metastasis." (PMID 31416203, 2019). "For breast cancer, ectopic secretion of MMPs family, such as MMP-1, MMP-2 and MMP-9, as well as VEGF, angiopoietin-like-4 (Angptl4), and COX-2, could degrade and destroy vascular endothelial cell junctions to promote tumor cells metastasis." (PMID 30819235, 2019). "In this study, we found that STAT3 could also mediate IL-6-induced MMP2 and MMP9 expression and breast cancer cell migration." (PMID 31409371, 2019). "Based on the in vivo results, immunohistochemistry analysis further revealed that MMP-2 and MMP-9 expressions were reduced in the lung colonization lesions after BA treatment, implying that BA might diminish the aggressiveness of breast cancer cells in vivo." (PMID 31531187, 2019). "In addition, a high activity of MMP-2 and MMP-9 has been observed in the serum and tissues of patients with breast cancer compared to healthy individuals." (PMID 31554180, 2019). "Moreover, RT-PCR results showed that RSF EtOAc significantly downregulated MMP-2 and MMP-9 expression, which play an important role in breast cancer metastasis." (PMID 31683960, 2019). "Interaction between MMP-2 and miR-29b may be useful as therapeutic target for breast cancer (BC)." (PMID 30357755, 2019). "S100A4 was also shown to increase MMP2 levels in MDA‐MB‐231 and MDA‐MB‐468 breast cancer cells." (PMID 30980596, 2019). "Early studies showed that both MMP-2 (gelatinase-A) and MMP-9 (gelatinase-B) can cleave Gal-3 at specific residues within its N-terminal tail (Ala62-Tyr63), leading to reduced cell surface expression in human breast cancer cell lines." (PMID 31440233, 2019). "Thus, due to the paucity of studies in the literature, further studies with a larger sample size are necessary to improve knowledge of the role of MMP-2 and MMP-9 in the progression and prognosis of breast cancer." (PMID 31839881, 2019). "Downregulation of MMP-2 and MMP-9 expression induced by MPPa-PDT may enhance the therapeutic efficacy for breast cancer by restricting metastasis by upregulating cell apoptosis and necrosis." (PMID 31783821, 2019). "On the other hand, the majority of studies in literature have investigated serum concentrations of MMP-2 and MMP-9 and showed a higher concentration of these serum proteins in breast cancer patients than in women with fibroadenoma, corroborating data of immunohistochemical expression." (PMID 31839881, 2019). "Notably, WISP2 was a negative regulator of migration and invasion via regulation of MMP-2 (matrix metalloproteinase-2), and MMP-9 in breast cancer cells." (PMID 30808397, 2019). "In particular, metastatic breast cancer cells promote osteoclasts formation and activity by secreting osteolytic interleukins (ILs) such as IL-8 and IL-11,as well as TNFαand matrix metalloproteinases (MMP1, MMP2),which are involved in bone matrix destruction." (PMID 30126457, 2018). "In other words, interaction of Plac1 and Furin may be sufficient to alter this pathway, further enhancing MMP2 and MMP9 protein levels to promote the invasion and metastasis of breast cancer cells." (PMID 29704427, 2018). "In addition, PKM2 can phosphorylate STAT3, a regulator of EMT markers, such as MMP-2, MMP-9, and Snail, in breast cancer cells." (PMID 30404206, 2018).
breast cancer (continued). "Low expression levels of MMP-2 and MMP-9 in breast cancer patients may indicate a relatively good patient prognosis." (PMID 30518369, 2018). "Moreover, CHOP and MMP2 expression were upregulated in tumors with low IGF-1R, whereas expression was unchanged in TNBC compared to ER+/PR+ breast cancer revealing CHOP and MMP2 are more correlated with IGF-1R levels than with hormone receptor status." (PMID 30458886, 2018). "A meta-analysis including 4944 breast cancer patients revealed that overexpression of MMP-2 was not related to shorter overall survival." (PMID 29949618, 2018). "Further analysis is necessary to examine whether A77636′s action on Rac1 GTPase and/or RhoA GTPase may regulate matrix metalloproteinases such as MMP2 and MMP9 that may drive migration of breast cancer cells." (PMID 28374823, 2017). "High levels of MMP-2 and MMP-9 have been related to breast cancer invasion." (PMID 29050342, 2017). "The results of this study show that low-risk tumors had less MVD and lower VEGF, MMP-2, and MMP-9 expression levels compared with non-low-risk breast cancers." (PMID 29371992, 2017). "Low-risk breast cancers showed significantly lower matrix metalloproteinase (MMP)-2 expression (P = 0.000), lower MMP-9 expression (P = 0.001), and lower microvessel density (MVD) values (P = 0.008) compared with non-low-risk breast cancers." (PMID 29371992, 2017). "To further elucidate the molecular mechanism through which GDF15 enhances breast cancer cell invasion, we measured expression levels of matrix metalloproteinases (MMP) MMP2 and MMP9, which are transcriptional targets of FoxM1 and mediators of cancer cell invasion." (PMID 29212236, 2017). "Low-risk breast cancers demonstrated lower MVD, VEGF, MMP-2 and MMP-9 than non-low-risk breast cancers." (PMID 29371992, 2017). "An analysis of MMP2 revealed no significant change in gene expression or protein levels by IHC, even though several breast cancer studies have found an upregulation of MMP2 in the tumour stroma of human patients." (PMID 28531107, 2017). "The molecular mechanism of its anti-invasive effect could be the inhibition of matrix metalloproteinase-2 (MMP-2) and MMP-9 in human breast carcinoma cells." (PMID 28404892, 2017). "In breast cancer, MMP9 was reported to be highly expressed, in contrast to MMP2." (PMID 26921265, 2016). "Due to the fact that Asp-UA could decrease the expression of CAMs, we further assessed the expression of crucial proteins including MMP-2, MMP-9 and COX-2, which are critical functional molecules within the tumor invasion process in breast cancer cells." (PMID 27683033, 2016). "Thus far, our data have established that Rab40b is required for MMP2 and MMP9 targeting to the invadopodia and for breast cancer metastasis in vitro and in vivo." (PMID 27789576, 2016). "Moreover, expression of MMP-2 and MMP-9 is upregulated in many cancer types, including lung cancer, breast cancer, and glioma, and is considered an important prognostic factor." (PMID 27081042, 2016). "Accordingly, treatment with low-dose (10–20 μg/mL) EtOAc extracts for 24 h decreased cell migration by downregulating protein expression of MMP2, MMP9, cyclin B, vimentin, and snail protein in MDA-MB-231 cells, indicating decreased breast cancer cell growth both in vivo and in vitro." (PMID 27078842, 2016). "For instance, co-culture of macrophages with ovarian or breast cancer cell lines was found to increase the expression of MMP2 and MMP9 in macrophages, but not in tumor cells, to promote tumor invasiveness." (PMID 27487154, 2016). "Moreover, gallic acid has also been shown to downregulate the AKT/small GTPase signalling pathway and MMP (MMP-2, MMP-9) expression in gastric carcinoma, osteosarcoma, glioma, cervical and breast cancer." (PMID 28933410, 2016). "It is still unclear whether Rab40b also regulates MMP2 and MMP9 targeting in other cancers or whether it is limited to breast cancer." (PMID 27789576, 2016).
breast cancer (continued). "Second, both ZEB1 and VEGFA may induce the production of matrix metalloproteinases (MMPs), such as MMP-2 and MMP-9, in breast cancer cells." (PMID 26882471, 2016). "Our results indicate that as a promising anti-cancer agent, PMS may inhibit growth and metastasis of breast cancer by inhibiting the activity of MMP9 and MMP2." (PMID 26674531, 2015). "In this study, we determined whether BRACs inhibited breast cancer cell invasion by suppressing RAS/RAF/MAPK signaling, and the possible involvement of MMP2 and MMP9, which are regulated by JNK, was involved in the antimetastatic activity of BRACs." (PMID 26649302, 2015). "Moreover, we provided evidence that elevated STAT3 signaling mediates upregulation of MMP-2/9 and confers increased invasiveness in SK-BR-3/EPR breast cancer cells." (PMID 26501276, 2015). "Interestingly, TGF-β1 is reported to induce MMP-2 and MMP-9 activity in a variety of human cancers, including breast cancer." (PMID 25658913, 2015). "Previous studies proved that high MMP-2 and MMP-9 expression can promote breast cancer invasion." (PMID 26599012, 2015). "It has been suggested that TGF-β can cause epithelial-mesenchymal transition (EMT) via Smad pathway and its downstream effect genes, and also up-regulate plasminogen activator, MMP-2 and MMP-9, which degrade extracellular matrix, allowing for subsequent migration of breast cancer cells." (PMID 26597083, 2015). "MMP-2, MMP-9 and eukaryotic transcription factor-1(ETS-1) co-expression might be used as a poor prognostic factor in breast cancer patients." (PMID 26674531, 2015). "In addition, it also remained conflicting as to the influence of MMP-1, MMP-2, MMP-11, MMP-13 and MMP-14 expression on the survival of breast cancer patients." (PMID 26270045, 2015). "Therefore, MMP-2 and MMP-9 are key factors in CHD1L that promote invasiveness of breast cancer cells." (PMID 26599012, 2015). "Therefore TAM and 3BP the ability to modulate MMP-2/MMP-9 activity and VEGF levels in human breast cancer in vitro." (PMID 26526196, 2015). "Recently, a growing body of evidence has been presented to show that SDF-1α/CXCR4 stimulation also leads to the secretion of various proteases, such as MMP-2 and MMP-9 by the breast cancer cells, which are then used to degrade the extracellular matrix, thereby facilitating cellular motility." (PMID 25753200, 2015). "Since PMS can target combine with MMP9 and MMP2, we assumed that PMS could suppress the growth and metastasis of breast cancer via regulating the activity of MMP9 and MMP2." (PMID 26674531, 2015). "IL-17 promotes tumor proliferation, survive and metastasis by up regulating angiogenesis factors VEGF, CXCL8, MMP2 and MMP9, while at the same time, it significantly suppresses apoptosis in several human breast carcinoma cell lines, such as 4T1, MDA-MB-231 cells." (PMID 26313265, 2015). "Moreover, our study indicated that, after TLR4 stimulation, breast cancer cells produced higher amounts of MMP-2, MMP-9 and VEGF, and as stimulus concentration increased within a certain range, the production of MMP-2, MMP-9 and VEGF also increased." (PMID 25299052, 2014). "Taken together, these results indicate that the E2F1-mediated expression of MMP2, MMP9, MMP14, and MMP15 might be repressed by KDM2A, eventually hindering the migration and invasion of breast cancer cells." (PMID 25029110, 2014). "In addition, CXCR7 regulated breast cancer metastasis by enhancing expression of metalloproteinases (MMP-9, MMP-2) and vascular cell-adhesion molecule-1 (VCAM-1)." (PMID 24886617, 2014). "Furthermore, Twist protein expression correlated with MMP-2 and MMP-9 protein expression in the breast cancer tissue specimens." (PMID 23935727, 2013). "MMP-2 and MMP-9 have been related to poor prognosis and lung metastasis in breast cancer." (PMID 24245968, 2013).
breast cancer (continued). "Moreover, baicalin suppressed cell migration and invasiveness in breast cancer MDA-MB-231 cells by down-regulating p38 MAPK pathway and consequently MMP-2 and MMP-9 expression." (PMID 24167634, 2013). "Moreover, we further investigated the correlation between Twist and gelatinase (MMP-2 and MMP-9) expression in breast cancer." (PMID 23935727, 2013). "Altered expression of Twist, MMP-2 and MMP-9 proteins was observed in breast cancer tissue." (PMID 23935727, 2013). "Given the putative role of both VEGF and MMP2 in the process of tumor growth and metastasis and recent data demonstrating the ability of FLLL32 to abrogate breast cancer xenograft growth in mice, future work assessing the effects of FLLL32 in mouse models of OSA is warranted." (PMID 21443800, 2011). "In addition, estrogen has been shown to regulate the activity of MMP-2 and MMP-9 in ER+ breast cancer cells and a positive correlation between ER-α expression and the effects of estrogen on MMP gene expression in breast cancer cells." (PMID 21267453, 2011). "MMP-2 and MT1-MMP could be further evaluated as future biomarkers for predicting the progression and prognosis of canine mammary tumors." (PMID 21726449, 2011). "PGE2 may also induces cell migration and invasion by upregulation of matrix metalloproteinase 2 (MMP2) via an ERK-ETS1 cascade in pancreatic cancer cell lines and upregulation of CCR7 via PTGER2 (EP2) and PTGER4 (EP4) in breast cancer cell lines." (PMID 24213116, 2011). "Here, we propose a more comprehensive approach by analyzing the expression levels of several MMPs (MMP-2, MMP-9 and MMP-14) and MMP inhibitors (TIMP-1, TIMP-2 and RECK) in different models (five human breast cancer cell lines, 72 primary breast tumors and 30 adjacent normal tissues)." (PMID 19144199, 2009). "Efficient reduction of MMP-2 and -9 levels was observed during in vitro treatment of MCF-7 breast cancer cells with the aromatase-inhibitor letrozole suggesting that this inhibitor suppresses both breast cancer growth and invasion." (PMID 19531263, 2009). "Here, we proposed a more extensive approach by analyzing the mRNA expression levels of different MMPs (MMP-2, MMP-9 and MMP-14) and MMP inhibitors by qRT-PCR (TIMP-1, TIMP-2 and RECK) in several models (five human breast cancer cell lines, 72 primary breast tumors and 30 adjacent normal tissues)." (PMID 19144199, 2009). "Our findings have showed that BER suppresses the growth, migration and invasion in highly-metastatic human breast cancer cells by possibly inhibiting Akt and NF-κB signaling with their upstream target c-Met and downstream targets Bcl-2/Bax, osteopontin, VEGF, MMP-9 and MMP-2." (PMID 19796390, 2009). "We analyzed the expression levels of MMP-2, MMP-9 and MMP-14 and their inhibitors (TIMP-1, TIMP-2 and RECK) by quantitative RT-PCR (qRT-PCR) in five human breast cancer cell lines presenting increased invasiveness and metastatic potential, 72 primary breast tumors and 30 adjacent normal tissues." (PMID 19144199, 2009). "In this study, we have determined whether irradiation of a reconstituted basement membrane (Matrigel; Becton Dickinson, Bedford, MA, USA) could enhance the expression of MMP-2, MT1-MMP and TIMP-2 from breast cancer cells." (PMID 17987037, 2007). "The MCF-7 cells do not also express the αvβ3 integrin and consequently no MMP-2 activity was detected on surface of this breast cancer cell line." (PMID 17987037, 2007). "This prompted us to test the hypothesis that the individual expression or the balance between MMP-2, MMP-14 and TIMP-2 expression may help to predict breast cancer prognosis." (PMID 16776850, 2006). "However, slightly lower levels of TGFβ1 (P<0.0001) and MMP-2 (P=0.03) and a small increase of MMP-9 (P=0.001), OPG (P=0.003) and CTX (P=0.0007) have been detected in breast carcinoma patients." (PMID 16880790, 2006). "MMP-2 and – 8 were not expressed in detectable amounts by breast cancer cells, as assessed by RT-PCR." (PMID 15701164, 2005).